LEP (leptin)
Diseases named in the same sentence as LEP in open-access papers (continued):
Sharing a sentence is not in itself a finding about the gene and the disease.
diabetes (continued). "Oxidative stress is increased in diabetes with leptin administration reportedly improving insulin sensitivity in normal and diabetic rodents." (PMID 20671928, 2010). "In the female patients, serum leptin was higher in those with pre-diabetes (14.09 [2.8–44.4]) than in the controls." (PMID 17617917, 2007). "It is evident that those in the diabetes group were significantly older (p < 0.0001), with higher fasting glucose and leptin levels (p < 0.0001, 0.012 respectively) than those in the pre-diabetes and control groups." (PMID 17617917, 2007). "Taken together, these results show that in RINm5F cells leptin induces a set of genes that is also expressed in β-cells in models of diabetes and β-cell destruction." (PMID 17521427, 2007). "It is observed that the leptin level rises with longer duration of diabetes." (PMID 40630340, 2025). "For example, leptin has been found to be higher in men with diabetes compared with control, and that leptin may induce bone growth by stimulating osteoblast proliferation and differentiation in vitro, and inhibiting osteoclastogenesis." (PMID 40566336, 2025). "In models controlling for BMI, percentage body fat, diabetes, cardiovascular disease, C-reactive protein, IL-6, and physical activity, subjects in the highest quintile of leptin declined less over four years on the modified mini-mental state examination (MMSE)." (PMID 41516046, 2025). "We investigated whether the peripheral co-administration of leptin and liraglutide (a glucagon-like peptide-1 receptor agonist) improved glucose metabolism in a mouse model of insulin-dependent diabetes mellitus (IDDM)." (PMID 40429740, 2025). "Compared to CGL1, CGL2 patients have lower leptin levels, an earlier onset of diabetes, mild cognitive impairment (which may be related to increased seipin expression in the brain), higher insulin levels, and thus insulin resistance." (PMID 40508223, 2025). "Novel studies highlights leptin’s role in development of various illness: diabetes, cardiovascular: cardiac diseases, diabetic cardiomyopathy, cardiac fibrosis, vascular dysfunction, and skin diseases: psoriasis, systemic lupus erythematosus, and hidradenitis suppurativa." (PMID 40426925, 2025). "A trend in positive association between leptin levels and diabetes was also observed, although it did nor result statistically significant." (PMID 40740781, 2025). "Indeed, simply restoring plasma leptin levels to normal is insufficient to normalize glycemia in a rodent model of uncontrolled diabetes (although it does ameliorate ketosis)." (PMID 40759579, 2025). "A 2021 Turkish clinical study that used a cross-sectional study design found significantly lower serum leptin in MS patients (6.12 ± 5.34 ng/mL) than in controls (13.02 ± 8.25 ng/mL), even after excluding individuals with diabetes, dyslipidemia, or liver dysfunction." (PMID 41516046, 2025). "Another field of research is the association of maternal adiposity with increased leptin production, hyperinsulinemia, and hyperglycemia, even in the absence of diabetes." (PMID 40077761, 2025). "The VMN is also a key target for leptin’s ability to ameliorate diabetes." (PMID 40759579, 2025). "Additionally, the tissue-specific expression of adipokines such as AdipoQ in sarcopenia and LEP in diabetes further underscores the pathology-specific regulatory mechanisms that modulate mitochondrial function through endocrine signaling." (PMID 40869253, 2025). "However, in P10, diabetes remained poorly controlled and because of low serum leptin levels (5.1 μg/L; reference >12 μg/L), recombinant human metraleptin therapy was started with good effect on glucose regulation, hepatic steatosis, and albuminuria." (PMID 40590205, 2025). "Their mammalian‐like ghrelin and leptin activity regulates lipid storage and metabolism, and their insulin‐producing cells share signaling pathways with mammals, making zebrafish suitable for mimicking diabetes." (PMID 41030912, 2025).
diabetes (continued). "Finally, the divergent behavior of leptin positively correlated only in diabetes, while AdipoQ was only positively correlated in sarcopenia; this points to pathology-specific regulatory axes layered atop this shared network." (PMID 40869253, 2025). "However, plasma leptin levels were lower in patients with metabolic comorbidities, with a statistically significant trend noted only among those with diabetes." (PMID 40943431, 2025). "Also, we recommend performing a comparison of these markers with other adipokines, such as adiponectin and leptin, which have a valuable effect on diabetes." (PMID 39979315, 2025). "Subsequently, correlation analysis revealed a bifurcated adipokine landscape—classical regulators EP, ITLN1, and RBP4 were observed in both datasets, plus LEP in diabetes—maintaining strong positive ties to mitochondrial hubs, signifying a conserved energy–support axis." (PMID 40869253, 2025). "We did not observe interaction between the mediators (leptin, diabetes and hypertension) and TBF or BMI in the association with CKD or moderately increased albuminuria." (PMID 38627329, 2024). "A literature review suggested that chronic alcohol consumption may induce leptin resistance due to prolonged elevation of leptin, potentially contributing to the development of diabetes." (PMID 39664526, 2024). "The higher incidence of diabetes in obese individuals, combined with the known effects of adipokines like leptin on appetite and insulin resistance, raises the question of whether there is a relationship between adipokines and appetite traits in adults." (PMID 39539026, 2024). "Additionally, an increase in adiponectin and a decrease in leptin was observed after four months of intervention in patients with diabetes following an L-dAGEs diet compared to a standard S-AGE diet." (PMID 39518960, 2024). "Based on our analysis of 21 RCTs, we found that supplementing with L-carnitine can lead to significant improvements in various health markers, such as TG, LDL, FBG, HbA1c, HOMA-IR, CRP, TNF-α, weight, BMI, BFP, and leptin levels in patients with diabetes and glucose intolerance." (PMID 39085907, 2024). "Leptin has been suggested to be a factor in the development of metabolic disorders such as diabetes, and might act as an early marker of metabolic disorder or complications." (PMID 38773198, 2024). "Similarly to leptin we built a logistic model for the presence of baseline brain infarcts, using age, gender, adiponectin levels, diagnosis, BMI, diabetes, dyslipidaemia, hypertension, smoke and atrial fibrillation as independent predictors." (PMID 38686200, 2024). "Our random order three plus three-month long cross-over diet intervention study in people affected by type 2 diabetes resulted in lower body weight, leptin and HbA1c, and higher satiety per calorie from practising the Paleolithic diet as compared to the diabetes diet." (PMID 39232748, 2024). "We found a statistically higher concentration of leptin in the group of children with newly diagnosed diabetes compared to the children in the DM1n group (11.19 ± 52.16 vs 7.75 ± 7.94 ng/mL, p=0.046) and lower than in healthy children (11.19 ± 52.16 vs 20.94 ± 23.29 ng/mL, p<0.001)." (PMID 37670877, 2023). "Additionally, the inclusion of leptin in a conventional risk model (including age, sex, BMI, LVEF, and presence of diabetes) significantly improved the prediction of MACE in patients with stable CAD (C-index 0.81 vs. 0.78)." (PMID 36676179, 2023). "Thus, leptin increases glucose metabolism in the skeletal muscles and brown adipose tissue and can improve blood glucose levels in uncontrolled diabetes." (PMID 37176525, 2023). "Leptin and adiponectin regulating glucose metabolism also take part in the development of diabetes." (PMID 37444627, 2023). "Insufficient leptin signaling in mammals leads to obesity, diabetes, and hyperphagia." (PMID 37058498, 2023). "In the same analysis, leptin was found to be similar in the prediction of diabetes." (PMID 36901837, 2023).
diabetes (continued). "T1DM mice are leptin deficient due to decreased fat mass resulting from uncontrolled diabetes unlike humans with T1DM that receive insulin therapy." (PMID 36674935, 2023). "Second, excess body fat results in the dysregulation of a wide range of adipokines including classic hormones such as leptin, which may contribute to diabetes via the alteration of glucose metabolism, lipid metabolism and inflammation." (PMID 36747216, 2023). "In addition, leptin has been shown to be useful prognostic factor in weight gain and in the development of type 2 diabetes mellitus." (PMID 36967781, 2023). "In addition, an increasing number of new biomarkers, such as cortisol, leptin, adiponectin and human placental lactate (hPL), have been found to be related to the incidence of insulin resistance-induced diabetes." (PMID 37308962, 2023). "Lower levels of leptin were found in children with diabetes compared to healthy children." (PMID 37670877, 2023). "The development of diabetes under these conditions may be due to the influence of adipokines (leptin and resistin), as they stimulate or reduce the secretion of insulin (a hormone that controls serum glucose levels)." (PMID 36875280, 2023). "Moreover, we found a statistically higher concentration of leptin in the group of children with newly diagnosed diabetes compared to children in the diabetic group with poor metabolic control and a decrease than in healthy children." (PMID 37670877, 2023). "Therefore, the aim of the present study was to evaluate the status of serum leptin and biologically active leptin (bioLEP - functional leptin) levels in children with three forms of diabetes (newly diagnosed, well and poorly controlled) and healthy controls." (PMID 37670877, 2023). "Furthermore, the leptin level has been reported to be lower before the start of insulin treatment in patients newly diagnosed with diabetes than in healthy controls." (PMID 37670877, 2023). "Serum leptin may be a good prognostic factor of energy malnutrition, except for the cases of low creatinine clearance, diabetes, end-stage disease, or thyroid disease." (PMID 36978817, 2023). "More studies are needed to explore the complex pathophysiological mechanisms in diabetes mellitus, and specifically focusing on investigating whether lowering TG levels would decrease leptin SR level and protect β-cell from its deleterious effect." (PMID 36950695, 2023). "Furthermore, we discovered that increased visceral fat and leptin levels predicted diabetes similarly to HbA1c." (PMID 36901837, 2023). "Diabetes-associated cognitive decline (DACD), one of the complications of type 2 diabetes (T2DM), correlates significantly with the disorder in glycolipid metabolism, insulin/leptin resistance, and accumulation of β-amyloid (Aβ)." (PMID 35721013, 2022). "The correlation between leptin and diabetes has been frequently discussed." (PMID 36295022, 2022). "In addition to this, diabetics were found to have a higher ratio of leptin/ghrelin; in our study we noticed a positive correlation with the HOMA-IR." (PMID 36355134, 2022). "The identification of glucose uptake mediators overcoming leptin and insulin resistance could provide new strategies for the treatment of the major form of type 2 diabetes mellitus." (PMID 35159237, 2022). "The proposed novel classification of diabetes may contribute in selecting a suitable population for leptin therapy." (PMID 34996484, 2022). "In a rodent pre-diabetes model, hyperexcitability was found in the tibial nerve which correlated with weight, insulin resistance, and insulin and leptin levels, suggesting that metabolic changes may drive early axonal dysfunction." (PMID 35565656, 2022). "A diabetes prevention program conducted in high-risk individuals in Leicestershire, United Kingdom, indicated a positive relationship between leptin levels and self-reported sitting time, independent of physical activity intensity." (PMID 36698957, 2022).
diabetes (continued). "After adjusting for age, diabetes, high-sensitivity C-reactive protein, intact parathyroid hormone, LTM, and FM, multiple linear regression analysis revealed that serum leptin levels were significantly positively associated with REE in men rather than in women (P < 0.05)." (PMID 35369060, 2022). "Increased baseline leptin levels are associated with an increased risk of diabetes in men but not in women among Japanese Americans." (PMID 35619087, 2022). "The hypothalamus may play a key role in the early onset of diabetes because it is involved in the control of glucose homeostasis and energy balance, as well as appetite regulation by leptin and insulin." (PMID 36297523, 2022). "Diabetes seems to be the shared factor between leptin and SS." (PMID 36295022, 2022). "The association of leptin with diabetes but not chorioamnionitis is consistent with a more robust role for leptin in endocrine than infectious conditions, and a relatively diminished role for leptin in perinatal inflammatory cascades." (PMID 35197933, 2022). "Third, diabetes is accompanied frequently by hyperleptinemia as a result of leptin resistance, and leptin signaling could participate in the pathogenesis of hematologic malignancy." (PMID 34638244, 2021). "Demographic data, height, weight, body mass index, blood glucose, thyroid-stimulating hormone, alanine transaminase, aspartate transaminase, creatinine, low-density lipoprotein, leptin, adropin levels, presence of hypertension, diabetes mellitus, coronary artery disease were recorded." (PMID 34664869, 2021). "The LEP pathway gene SNP-SNP interactions analysis results have statistical significance and illustrate that the SNP-SNP interactions (gene interactions) are part of the genetic structure of type 2 diabetes mellitus." (PMID 34589546, 2021). "Several studies report higher plasma leptin levels diabetes mellitus." (PMID 34055923, 2021). "Several studies have used leptin gene transfer to treat diet-induced and age-related obesity and non-insulin-dependent diabetes mellitus (NIDDM) using animal models; however, little work has been carried out in insulin-dependent diabetes mellitus and neuroendocrine alterations." (PMID 34947993, 2021). "Independently of the cause of malnutrition, it is known that weight loss is associated with perturbances in the serum concentration of adipokines, the most studied of which are adiponectin and leptin, both in SSc and other conditions such as anorexia or diabetes." (PMID 33816531, 2021). "Moreover, leptin plays a part in lactation, bone density, the immune system, diabetes treatments, and hypertriglyceridemia." (PMID 35027962, 2021). "Then, the disruption of leptin signaling may contribute to the development of metabolic complications, including diabetes and cardiovascular diseases." (PMID 34681831, 2021). "Using a population-representative birth cohort, we aimed to examine the associations among maternal metabolic conditions (maternal diabetes, pre-pregnancy overweight, and HDP), leptin concentrations in umbilical cord serum, and later autistic symptoms in children." (PMID 35185642, 2021). "Diabetes decreased serum level of leptin compared with the control group." (PMID 33920401, 2021). "Diabetes involves metabolic alterations, hormonal imbalances particularly of insulin/insulin growth factor-1 and adiponectin/ leptin, and immune response such as elevated levels of pro-inflammatory cytokines like tumor necrosis factor-a (TNF-α), and all these features it shares with cancer." (PMID 34225729, 2021). "The effect of sitagliptin on reducing BMI and the occurrence of hypoglycemia in obese patients with insulin treatment-induced diabetes mellitus might be correlated with decreased leptin levels and increased adiponectin levels." (PMID 34446063, 2021). "The leaves of LPR could be used for the treatment of disorders such as diabetes, hypertension, epilepsy, and antiobesity, as well as improving leptin resistance in diet-induced obese rats." (PMID 33801901, 2021).
diabetes (continued). "AT1R is also required for leptin-sensitized metabolic control; therefore, this mice line could be a very useful model to study diabetes-related brain disorders." (PMID 34697992, 2021). "Moreover, preclinical and clinical trials are required to determine if MCS will be beneficial in the context of MetS/IR and/or T2DM, including in the study of leptin-based and insulin-derived models of diabetes." (PMID 34279477, 2021). "Some of these leptin sensitizers are in clinical use for diabetes therapy, such as amylin and pramlintide, that enhance leptin action, probably increasing IL-6 production in microglia ventromedial hypothalamic nucleus that in turn activates pSTAT3 signaling in LepR neurons." (PMID 34084149, 2021). "For example, in streptozotocin-induced diabetes rats, central administration of leptin can reverse hyperglycemia, regardless of insulin deficiency." (PMID 34063647, 2021). "Leptin is affected by sex hormones, and high levels of leptin are related to an increased risk of diabetes in men but not in women." (PMID 33002067, 2020). "The differential regulation of leptin signaling pathways in different organs may shed light on few facets of molecular interplay between inflammation, insulin resistance, diabetes, and intervertebral disc degeneration." (PMID 33396484, 2020). "Our data exhibit that infusion of MSCs and its combination therapy with insulin might ameliorate diabetes signs by changing the amount of leptin and subsequent changes in the expression of neuropeptide Y and melanocortin-4 receptor." (PMID 32405365, 2020). "The positive association with DPN persisted after adjustment for eGFR, diabetes duration, and use of lipid-lowering medications (model 3) for serum adiponectin (OR: 1.72, 95% CI: 1.02–2.89, P=0.041), but not for leptin (OR: 1.02, 95% CI: 0.99–1.06, P=0.220)." (PMID 33324342, 2020). "In exploratory analyses in PIVUS, the association between A-FABP and leptin was similar also in individuals without diabetes (n = 876, regression coefficient per SD increase 0.26, 95% CI 0.22–0.31, p < 0.001)." (PMID 32753620, 2020). "Pathways activated by leptin in the brain have neuroprotective roles also, leptin may be a potentially useful adjunct to insulin treatment in management of diabetes." (PMID 33585009, 2020). "Models 1, 2, 3 and 4 included adiponectin, leptin, resistin and visfatin respectively as predictors whiles controlling for confounding factors like age, parity, BMI, relative with hypertension, and family history of diabetes and preeclampsia." (PMID 33014422, 2020). "Further adjustments for confounders for diabetes mellitus such as body mass index, hemoglobin A1c level, and adiponectin-to-leptin ratio, which were performed using a Cox proportional hazards model, indicated that the OC level was an independent risk factor for diabetes." (PMID 32605143, 2020). "LEP can alleviate diabetes via inhibition of the hypothalamic-pituitary-adrenal axis." (PMID 32405365, 2020). "Taking most of the factors associated with PE and adjusting for these potential confounding variables (age, parity, BMI, family history of diabetes and preeclampsia), adiponectin and resistin were found to be significant and better predictors of PE than leptin and visfatin." (PMID 33014422, 2020). "Additionally, ABA reduced plasma levels of leptin and resistin, two notable adipokines tied to the diminished uptake of glucose in diabetes and impaired IRS-1 signaling." (PMID 32591558, 2020). "However, during diabetes Pomc was elevated in the hindbrain, perhaps suggesting a counter-regulatory effect and intact insulin and/or leptin signalling up to this point in the pathway." (PMID 31601900, 2019). "Heritable sex-related differences in leptin pulses might be as integral to diabetes onset as conventional means and biochemical action." (PMID 31661517, 2019).